APP (amyloid beta precursor protein)
Diseases named in the same sentence as APP in open-access papers (continued):
Sharing a sentence is not in itself a finding about the gene and the disease.
osteoarthritis (2 papers, 2011 to 2015). A noninflammatory degenerative joint disease occurring chiefly in older persons, characterized by degeneration of the articular cartilage, hypertrophy of bone at the margins and changes in the synovial membrane. "We report that localized induction of osteoarthritis in the young adult APP/PS1 mouse model of AD leads to glial activation as well as acceleration and exacerbation of AD plaque pathology." (PMID 21899735, 2011). "We found that Aβ plaques appeared earlier in APP/PS1 mice with osteoarthritis, in significantly larger numbers at all time points examined." (PMID 21899735, 2011). "Another study assessed the impact of osteoarthritis on AD pathology in APP/PS1 mice." (PMID 25802557, 2015). "At 8 months of age (6 month time point), APP/PS1; Col1-IL1βXAT mice suffering from osteoarthritis displayed increased numbers of Aβ plaques throughout their brain compared to age- and gender- matched APP/PS1 mice, with an apparent preponderance of large diameter (> 100 μm) plaques." (PMID 21899735, 2011). "Overall, our data show that the induction of osteoarthritis in young adult APP/PS1;Col1-IL1βXAT transgenic mice exacerbates and accelerates the development of AD pathology, suggesting that peripheral inflammation may be associated with increased risk for AD pathology." (PMID 21899735, 2011). "Concomitant with the accelerated formation of Aβ plaque deposition in the APP/PS1; Col1-IL1βXAT mice with osteoarthritis, we observed exacerbation of astrocyte and microglial activation as assessed by immunohistochemistry." (PMID 21899735, 2011). "APP/PS1 mice showed a modest level of Aβ pathology and neuroinflammation at 6 months of age, a time point when mice with osteoarthritis displayed a greater number of Aβ plaques." (PMID 21899735, 2011). "mRNA analysis for several murine cytokines and markers of glial activation revealed increased transcript levels in the APP/PS1; Col1-IL1βXAT mice with osteoarthritis compared to APP/PS1; Col1-IL1βXAT mice without osteoarthritis or wild type controls." (PMID 21899735, 2011). "Our results demonstrate that the presence of osteoarthritis, even in a small number of joints, induces the accumulation of Aβ plaques in the APP/PS1 model of AD at an age when such pathology is not present and enhances pathology at later times." (PMID 21899735, 2011). "It is interesting to note that neuroinflammation in our model of osteoarthritis was transient and resolved by the 6-month time point (8 months of age) in mice not carrying the APP/PS1 transgenes." (PMID 21899735, 2011). "The number of reactive glial cells was significantly increased in APP/PS1; Col1-IL1βXAT mice with osteoarthritis compared to APP/PS1 mice without osteoarthritis and wild type controls." (PMID 21899735, 2011). "Our studies demonstrate that induction of osteoarthritis in the APP/PS1 mouse model of AD at 2 months of age resulted in the development of Aβ plaques and neuroinflammation as early as 4 months of age, whereas there was lack of Aβ plaques in the absence of osteoarthritis." (PMID 21899735, 2011).
ovarian carcinoma (2 papers, 2016 to 2023). A malignant neoplasm originating from the surface ovarian epithelium. "But in our dataset, only one miRNA, namely miR-20a, targets APP to induce ovarian cancer." (PMID 27694936, 2016).
pancreatic adenocarcinoma (2 papers, 2021 to 2022). "Significantly, both pancreatic adenocarcinoma and cutaneous melanoma expressed elevated levels of APP and BACE2 compared to matched normal tissue." (PMID 33514748, 2021).
primary Sjogren’s syndrome (2 papers, 2019 to 2024). "By contrast AF102B is a neuroprotective M1 muscarinic agonist in use to treat Sjogren’s syndrome which has been shown to induce APP(s) secretion resulting from alpha-secretase activation of the non-amyloidogenic pathway of APP expression." (PMID 30823541, 2019). "Furthermore, scRNA-seq analysis of peripheral immune cells in patients with primary Sjogren’s syndrome highlighted not only enhanced CD74-COPA interactions between monocytes and naive B cells, but also CD74-amyloid beta precursor protein (APP) interactions between monocytes and memory B cells." (PMID 39493449, 2024).
proliferative diabetic retinopathy (2 papers, 2023 to 2025). Advanced retinopathy due to diabetes mellitus characterized by the formation of new vessels in the retina. "In proliferative diabetic retinopathy (PDR), pericytes exhibit global communication through the APP signaling pathway, with APP-CD74 being the major ligand–receptor pair and microglia serving as one of the key receiving cells." (PMID 40650067, 2025).
psychosis (2 papers, 2025). "APP has not been previously reported in relation to psychosis." (PMID 40943654, 2025).
retinal diseases (2 papers, 2023). "Another small cluster of proteins (cluster 4) that suggest the role of neurodegeneration in these retinal diseases are APP and related proteins (e.g., CYTC, CLSTN1, SPP1, APLP2)." (PMID 36875133, 2023). "In addition, angiogenesis and neurodegeneration in retinal diseases could be attributed to APP-induced Aβ and neuroinflammation." (PMID 38328307, 2023).
sarcoma (2 papers, 2023 to 2024). A usually aggressive malignant neoplasm of the soft tissue or bone. "Further investigation highlighted the interaction between PCOLCE and the cell surface protein APP, with elevated APP transcripts correlating with reduced survival in sarcoma patients." (PMID 38389836, 2024). "According to the TCGA database, the elevated level of APP transcripts of patients with sarcoma is a poor prognostic marker." (PMID 36943734, 2023). "Notably, a high level of APP transcripts significantly reduced the survival rate of sarcoma patients (p=0.0051)." (PMID 36943734, 2023).
seborrheic keratosis (2 papers, 2021 to 2024). A common benign skin neoplasm usually affecting older individuals. "Interestingly, seborrhoeic keratosis, which is an age-related skin disease prevalent in regions of the body with high density of SGs, is associated with the over-expression of amyloid precursor protein (APP), a key player in the pathogenesis of senile AD." (PMID 34940576, 2021). "In addition, decreased expression of presenilin-1, which is involved in degrading the amyloid precursor protein (APP), has been associated with seborrheic keratosis and inflammatory skin disease in patients with AD." (PMID 38739932, 2024).
silicosis (2 papers, 2023 to 2025). Silicosis is a respiratory disease caused by breathing in (inhaling) silica dust. "Previous studies have shown that APP is abnormally expressed in silicosis, which is consistent with our results." (PMID 41561355, 2025). "It was found that CD68 and APP interacted with CD74 on CD31 in the silicosis group and the Tet group, but not in the normal group, the H2 group and the H2 + Tet group." (PMID 41561355, 2025).
Splenomegaly (2 papers, 2021 to 2025). Abnormal increased size of the spleen. "First, the possible cause of the splenomegaly observed in 3xTg-AD mice was hypothesized to be the expression of human APP and presenilin 1 (PS1) with familial AD mutations; still, the results in other APP/PS1 transgenic mice refuted this hypothesis." (PMID 40906020, 2025). "Interestingly the 5xFAD mouse model of AD, which has both APP and presenilin-1 gene modifications does not display splenomegaly." (PMID 34199639, 2021).
temporal lobe epilepsy (2 papers, 2020 to 2021). A localization-related (focal) form of epilepsy characterized by recurrent seizures that arise from foci within the temporal lobe, most commonly from its mesial aspect. "Even the infrequent seizures that spontaneously occur in transgenic mice expressing human amyloid precursor protein (APP) lead to persistent increases in ΔFosB in the hippocampus, similar to what we observed in patients with AD or temporal lobe epilepsy." (PMID 32536852, 2020).
thyroid cancer (2 papers, 2024 to 2025). "It has been found that the expression level of APP is increased in prostate, pancreatic and thyroid cancers; when APP expression was upregulated, the metastatic ability of tumor cells increased, which suggests that it is closely related to tumor growth and metastasis." (PMID 39090420, 2025). "Similarly, the PI3K/Akt pathway is involved in the upregulation of sAPPα secretion and APP expression in thyroid cancer." (PMID 39332525, 2024).
uveal melanoma (2 papers, 2023 to 2024). A melanoma derived from melanocytes of the uveal tract. "APP-CD74 signaling has been previously implicated in uveal melanoma, where high expression of APP was identified in UM primary tumors compared to lower APP and higher CD74 expression in metastatic UM tumors." (PMID 38106024, 2023).
Zika virus infection (2 papers, 2023 to 2024). "Despite one group suggesting that APP is an antagonist for ZIKV infection, the conclusion was made based on enhanced ZIKV viral RNAs in a medium of APP-null cells." (PMID 38535583, 2024).
Zinc deficiency (2 papers, 2021 to 2024). A deficiency of the essential metal Zinc; an essential cofactor for many enzymes. "WT control or APP/PS1 mice were fed a diet containing the recommended zinc intake levels for mice (35 mg/kg, ZN) or a diet that would induce a mild subclinical zinc deficiency (3 mg/kg, ZD)." (PMID 33597269, 2021). "We report no changes in plaque deposition induced through zinc deficiency; therefore, we hypothesized that zinc was modulating the response to the Alzheimer's amyloidopathy modeled by the APP/PS1 mice and not the amyloidopathy itself." (PMID 33597269, 2021).
AA amyloidosis (1 paper, 2023). Secondary amyloidosis is a form of amyloidosis, that complicates chronic inflammatory disorders (mainly rheumatoid arthritis) and is characterized by the aggregation and deposition of amyloid fibrils composed of serum amyloid A protein, an acute phase reactant. "A recent study of two affected Abyssinian cats and 195 controls from different breeds concluded a polygenic background of AA-amyloidosis in this breed and found variants in Amyloid Beta Precursor Protein gene (APP) and Transthyretin (TTR) in affected cats." (PMID 38136948, 2023). "APP and TTR are not located within the genomic regions surrounding the significantly AA-amyloidosis-associated SNPs in the present study." (PMID 38136948, 2023).
alcoholic hepatitis (1 paper, 2023). Acute hepatitis resulting from ingestion of alcohol. "The promoter regions of TTR and other negative APP contain HNF-4α binding sites, and this correlation has been observed in patients with alcoholic hepatitis." (PMID 36652164, 2023).
Alexander disease (1 paper, 2024). Alexander disease (AxD) is a rare neurodegenerative disorder of the astrocytes comprised of two clinical forms: AxD Type I and Type II manifesting with various degrees of macrocephaly, spasticity, ataxia and seizures and leading to psychomotor regression and death. "The top two models identified were APP/PS1 transgenic mice expressing mutant APP and PSEN1, and mice carrying a GFAP mutation that is causative of Alexander disease, a primary disorder of astrocytes in the CNS." (PMID 38236817, 2024).
angioedema (1 paper, 2018). Swelling involving the deep dermis, subcutaneous, or submucosal tissues, representing localized edema. "In proven C1-INH-HAE, genetic testing of APP and ACE deficiencies could potentially help in identifying patients with more frequent or more severe angioedema attacks." (PMID 30479631, 2018).
Anosmia (1 paper, 2021). An inability to perceive odors. "Overall, APP/PSEN1-Tg animals seem not to present a complete anosmia, although it seems that they display a loss of discrimination between odours, so this possible hyposmia together with working memory impairments could explain the indiscriminate investigation that transgenic mice display." (PMID 33795014, 2021).
anxiety disorder (1 paper, 2024). A category of psychiatric disorders which are characterized by anxious feelings or fear often accompanied by physical symptoms associated with anxiety. "Thus, APP exerts different pathological effects in MDD compared to MDD with anxiety disorder." (PMID 38926475, 2024). "Deferoxamine, Resveratrol, and zinc acetate target the amyloid precursor protein (APP) gene, which is upregulated in aging and was also found to be upregulated in both MDD with and without comorbid anxiety disorder through our analysis." (PMID 38926475, 2024).
autoimmune disease (1 paper, 2020). A disorder resulting from loss of function or tissue destruction of an organ or multiple organs, arising from humoral or cellular immune responses of the individual to their own tissue constituents. "Another mutual pathway comprising PDIA4, APP and CANX genes is an ER dependent mechanism observed in both neurodegenerative and autoimmune diseases." (PMID 33066537, 2020).
B-vitamin deficiency (1 paper, 2017). "Similar downregulation of PP2A methylation and concomitant phosphorylation of tau and/or APP in the brain of AD mice caused by dietary folate and B-vitamin deficiency and elevated homocysteine levels have been shown previously." (PMID 28422052, 2017).
brain edema (1 paper, 2020). Increased intracellular or extracellular fluid in brain tissue. "In addition, prevention of neuronal and axonal injury may also be another reason for LITUS to reduce APP expression and combat brain edema." (PMID 33281713, 2020).
calcific aortic valve disease (1 paper, 2025). "Interestingly, human APP and TGFBI are co-expressed in corneal cells and associate together in amyloid-like deposits in calcific aortic valve disease." (PMID 40676215, 2025).
cataract (1 paper, 2025). Partial or complete opacity of the crystalline lens of one or both eyes that decreases visual acuity and eventually results in blindness. "A cataract model was established in APP/PS1 [mutant amyloid precursor protein (APP) and a mutant presenilin-1 (PS1) gene] mice via lens puncture." (PMID 40580389, 2025).
cholestasis (1 paper, 2023). Impairment of the bile flow caused by obstruction within the liver, or outside the liver in the bile duct system. "Among them, HSP90AA1, TLR4, MMP2, APP, and NFKB1 were the crucial targets of FTA in the treatment of cholestasis." (PMID 37432229, 2023).
Chronic colitis (1 paper, 2025). A chronic inflammatory disease of the large intestine (colon, cecum and rectum). "To determine whether gut microbiota manipulation directly influences cognitive function, we performed fecal microbiota transplantation (FMT) in AD (APP/PS1 transgenic) mice using donor feces from healthy C57BL/6J mice (WT) or mice with DSS-induced chronic colitis." (PMID 40486731, 2025).
chronic hepatitis (1 paper, 2017). An active inflammatory process affecting the liver for more than six months. "Importantly these results elucidate aspects of copper as an initiating factor, introduce APP as candidate gene for copper-associated chronic hepatitis, and lastly shed light on the molecular background of (chronic) hepatitis." (PMID 28459846, 2017). "Increased expression of APP in the chronic hepatitis phase is presumed to be specific for chronic copper-accumulating disease as this is thought to be an adaptive response to prolonged high intracellular copper levels." (PMID 28459846, 2017).
chronic lung disease (1 paper, 2021). According to the definitions of the American and British Thoracic Societies, including pulmonary functional tests, X-rays, and CT scans for items such as fibrosis, bronchiectasis, bullae, emphysema, nodular or lymphomatous abnormalities. "Additionally, the combined role of APP and ELAVL-1 in chronic lung diseases and their effect on different macrophage subtypes are not known." (PMID 33478018, 2021).
chronic obstructive pulmonary disease (1 paper, 2022). A chronic and progressive lung disorder characterized by the loss of elasticity of the bronchial tree and the air sacs, destruction of the air sacs wall, thickening of the bronchial wall, and mucous accumulation in the bronchial tree. "A previous study has shown that the serum levels of amyloid-beta, which is produced by proteolysis of APP, are significantly increased in patients with chronic obstructive pulmonary disease with poor pulmonary function." (PMID 36440052, 2022).
co-infection (1 paper, 2014). "maxima co-infection compared with uninfected controls (ANXA1, HSP90B1, VEGFA, MTTP, TNFSF11B, TCF12, APP, and CXCL14)." (PMID 25504150, 2014).
congenital hypothyroidism (1 paper, 2025). A thyroid hormone deficiency present from birth. "APP, DDB1, MRPS5, and MRPL33 are hub genes with low expression levels in congenital hypothyroidism (CH)." (PMID 41169358, 2025).
coronary artery atherosclerosis (1 paper, 2020). "Studies in APP and APLP1/2 knockout (KO) mice suggest functional differences among the three family members and, significantly, a particular importance for APLP2 in the physiology of the cholesterol metabolism and coronary artery atherosclerosis." (PMID 32716039, 2020).
corticobasal syndrome (1 paper, 2020). Corticobasal syndrome (CBS) is a rare neurodegenerative disease characterized by multifaceted motor system dysfunctions and cognitive defects such as asymmetric rigidity, bradykinesia, limb apraxia, and visuospatial dysfunction. "Lastly, genes responsible for early onset AD (EOAD) like presenilin 1 (PSEN1) and amyloid precursor protein (APP) can give rise to atypical parkinsonism like corticobasal syndrome (CBS)." (PMID 33250855, 2020).
Dyscalculia (1 paper, 2022). A specific learning disability involving mathematics and arithmetic. "However, when comparing V717I alone with other APP mutations, we found that patients with the V717I mutation had a later onset and tended to have dyscalculia but had less damage in linguistic and visuospatial regions." (PMID 36313020, 2022).
dysplasia (1 paper, 2025). A usually neoplastic transformation of the cell, associated with altered architectural tissue patterns. "While Apik and APP mice developed adenocarcinoma in the antrum at the median age of 5 months, Arid and Ap16 mice developed dysplasia and eventually adenocarcinoma in the antrum at approximately 1 and 1.5 years, respectively." (PMID 40761291, 2025).
encephalopathies (1 paper, 2025). "First, a multicentre large CSF proteomic study would be required to confirm the co-upregulation of APOE and APP in CM patients relative to age-matched patients with non-plasmodial encephalopathies and healthy community controls." (PMID 39023792, 2025).
Ewing sarcoma (1 paper, 2021). A small round cell tumor that lacks morphologic, immunohistochemical, and electron microscopic evidence of neuroectodermal differentiation. "Our analysis identified TRIM25, APP, ELAV1, RNF4, and HNRNPL as ideal mRNA targets for Ewing sarcoma therapy." (PMID 34662337, 2021).
familial amyloidosis (1 paper, 2011). "Both tubulin α and β have been shown to associate with the amyloid deposits of familial amyloidosis and to bind to the Aβ sequence of APP." (PMID 21445266, 2011).
Fanconi syndrome (1 paper, 2015). "Uric acid reduction was correlated to drug exposure but not to plasma Aβ change, suggesting a mechanism distinct from inhibition of APP cleavage such as drug-induced Fanconi syndrome." (PMID 26064192, 2015).
fluorosis (1 paper, 2019). "The level of MDA in the brains of mice with fluorosis or carrying the APP/PS1 mutation were significantly higher than those in the corresponding control groups, whereas the activities of SOD and GSH-Px were clearly lower." (PMID 31010414, 2019).
Glucose Metabolic Disorder (1 paper, 2016). "In summary, this study used 18F-FDG microPET in combination with the MWM test to assess age- and brain region-specific changes of glucose metabolic disorder and explore their associations with learning and memory dysfunction in APP/PS1 Tg mice." (PMID 27763550, 2016).
grand mal seizures (1 paper, 2024). "Consistently, our results revealed that older APP mice required less time to achieve grand mal seizures." (PMID 38388921, 2024).